FFAR4 (free fatty acid receptor 4)
Diseases named in the same sentence as FFAR4 in open-access papers (continued):
Sharing a sentence is not in itself a finding about the gene and the disease.
colon cancer (6 papers, 2016 to 2024). "FFAR4 has been implicated in colon cancer progression by stimulation of cellular function." (PMID 35340411, 2022). "In vitro studies reported that the activation of FFAR4 signaling pathways promotes motile activity and angiogenesis in colon cancer cells." (PMID 37111137, 2023). "FFAR4 is overexpressed in colorectal cancer, and its activation enhanced cell migration and induced a pro-angiogenic response in colon cancer cells." (PMID 33113952, 2020). "Another study performed in a different murine model of colon cancer proposes the implication of FFAR4 on chemotherapy resistance by modifying the macrophage function and, in the same line, high levels of FFAR4 in breast tumors were associated to a reduced response to chemotherapy in patients." (PMID 33113952, 2020).
lung carcinoma (6 papers, 2019 to 2024). "Third, FFAR4 was also reported to possess tumor promoting properties in colorectal and pancreatic cancer, and a recent genome-wide association study showed that a genetic variant of FFAR4 was associated with increased risk for lung cancer." (PMID 30795784, 2019). "The clinical TCGA data showed a significant down-regulation of FFAR2, but not FFAR1, FFAR3, and FFAR4, in lung cancer, and a negative correlation with TLR2 and TLR3." (PMID 37287005, 2023).
osteoporosis (6 papers, 2015 to 2026). A condition of reduced bone mass, with decreased cortical thickness and a decrease in the number and size of the trabeculae of cancellous bone (but normal chemical composition), resulting in increased fracture incidence. "Thus, DHA-FFAR4 signaling is considered an impactful mechanism that suppresses bone resorption and stimulates bone formation, making FFAR4 an attractive therapeutic target in bone metabolic disorders such as osteoporosis, rheumatoid arthritis, and inflammatory osteolysis." (PMID 40807354, 2025). "Overall, the DHA-FFAR4 axis may provide a potential therapeutic target for osteoporosis, rheumatoid/osteoarthritis, and OTM-associated bone loss and should be followed up with further clinical experiments and the development of highly selective FFAR4 agonists to achieve precise therapeutic effects." (PMID 40807354, 2025).
Non-Alcoholic Fatty Liver Disease (5 papers, 2014 to 2025). "Finally, FFAR4 activation also leads to improvement of non-alcoholic fatty liver disease (NAFLD) in children." (PMID 25076939, 2014).
steatosis (5 papers, 2014 to 2024). Increased lipid within the cytoplasm of cells. "Our work indicates for the first time the steatosis-inhibiting effect of the FFAR4/GPR120 agonist, but we cannot ignore the limitations of this study." (PMID 36705799, 2024).
heart failure (4 papers, 2022 to 2024). Inability of the heart to pump blood at an adequate rate to meet tissue metabolic requirements. "Interestingly, eicosapentaenoic acid, but not docosahexaenoic acid, prevents fibrosis in pressure overload-induced heart failure, due to a potential role of the free fatty acid receptor 4 (Ffar4) linked to G-protein." (PMID 36276836, 2022). "In WT mice, the HFpEF-MetS diet significantly increased Ffar4 expression, a somewhat surprising finding given that we previously found that Ffar4 expression is decreased in human heart failure." (PMID 37075982, 2023). "Studies have shown a decrease in FFAR4 during heart failure, with Ffar4-null mice exhibiting aberrant oxylipin transcriptomics during cardiac pressure overload." (PMID 37108233, 2023). "In humans, the expression of FFAR4 decreases in cardiomyocytes with heart failure." (PMID 39062812, 2024). "The cardioprotective mechanisms of eicosapentaenoic acid in heart failure are related to its ability to activate NRF2 (nuclear factor erythropoietin 2 related factor 2), Ffar4 receptor (free fatty acid receptor 4), or GPR120 fibroblast receptors." (PMID 36276836, 2022).
pancreatic cancer (4 papers, 2017 to 2022). "In some tumors, FFAR1 and FFAR4 have the opposite effect; for example, FFAR1 activation inhibits the motile activity of pancreatic cancer and osteosarcoma cells, while FFAR4 activation promotes these activities." (PMID 35785152, 2022).
ovarian carcinoma (3 papers, 2018 to 2024). A malignant neoplasm originating from the surface ovarian epithelium. "Survival analyses of FFAR1 and FFAR4 in ovarian cancer (Kaplan–Meier plotter)." (PMID 35785152, 2022). "In agreement with data suggesting significant and strong co-expression of CX3CR1 with GPR65 and FFAR4 in specimens, western blot confirmed robust downregulation of GPR65 and FFAR4 in ovarian carcinoma cell lines transfected with CX3CR1-specific siRNAs." (PMID 29712888, 2018).
ulcerative colitis (3 papers, 2021 to 2025). An inflammatory bowel disease involving the mucosal surface of the large intestine and rectum. "Moreover, FFAR4 activation by GSK1376647 reduced the accumulation of lipids causing an amelioration of DSS-induced ulcerative colitis (UC)." (PMID 39432182, 2024).
COVID-19 (2 papers, 2022 to 2023). A disease caused by infection with severe acute respiratory syndrome coronavirus 2. "On the other hand, FFAR2 and FFAR4 have been shown to downregulate Th2 inflammatory pathways implicated in cytokine storm in severe COVID-19 cases, including inflammatory cytokines IL-1β and IL-6." (PMID 37515117, 2023).
esophageal cancer (2 papers, 2020 to 2022). A primary or metastatic malignant neoplasm involving the esophagus. "FFAR1 activation inhibits the migration and invasion in fibrosarcoma cells, whereas FFAR4 activation stimulates the migration and invasion of esophageal cancer cells." (PMID 35785152, 2022). "Moreover, as FFAR4 was found to be significantly elevated in human esophageal cancer cells serving as a positive regulator of malignant transformation, it may appear as an attractive early biomarker of esophageal carcinogenesis—especially in patients with ERD and BE." (PMID 33419235, 2020).
gastroesophageal reflux disease (2 papers, 2020 to 2023). A chronic disorder characterized by reflux of the gastric and/or duodenal contents into the distal esophagus. "Study demonstrated that enriched genes including IL1B, CXCR1, FFAR4, VIP (vasoactive intestinal peptide), and GATA3 have been identified as a key candidate genes in patients with gastroesophageal reflux disease." (PMID 38137330, 2023).
hepatoma (2 papers, 2019 to 2023). "Fatty acids were also shown to promote lipid droplet formation in Huh-7 hepatoma cells by activating FFAR4, which initially is independent of exogenous lipid uptake." (PMID 37422000, 2023).
liver disease (2 papers, 2021 to 2025). "More studies are required to establish that omega-3 FA-induced improvements in liver disease are mediated through FFAR4-dependent pathways." (PMID 33897464, 2021). "Furthermore, the expression of FFAR1 on hepatocytes and FFAR4 on hepatic Kupffer cells makes targeting these receptors as an intuitive strategy for treating liver disease." (PMID 33897464, 2021).
lung adenocarcinoma (2 papers, 2023 to 2024). A carcinoma that arises from the lung and is characterized by the presence of malignant glandular epithelial cells. "Although FFAR4 activation significantly inhibited the proliferation of lung adenocarcinoma cells, the underlying mechanism is unclear." (PMID 38243188, 2024). "In the current investigation, it was observed that the expression of FFAR4 was notably diminished in individuals diagnosed with lung adenocarcinoma, and this decrease in FFAR4 levels was found to be correlated with a more unfavorable prognosis." (PMID 38243188, 2024). "FFAR4 expression levels were downregulated in lung adenocarcinoma cell lines H1299 and A549 compared with normal lung epithelial cell line BEAS-2B." (PMID 38243188, 2024). "In summary, activation of FFAR4 exhibited a substantial inhibitory effect on the proliferation of lung adenocarcinoma cells and induced cell cycle arrest." (PMID 38243188, 2024). "Subsequently, the expression of FFAR4 mRNA was validated in both lung adenocarcinoma and paracancerous tissue obtained from patients with LUAD." (PMID 38243188, 2024). "Furthermore, the findings indicate that the activation of FFAR4 agonist had a marginal impact on the glycolytic capacity of lung adenocarcinoma cells, potentially due to insufficient energy provision." (PMID 38243188, 2024). "Additionally, the activation of FFAR4 was found to significantly impede the proliferation of lung adenocarcinoma cells, and this effect was mediated through its influence on mitochondrial metabolism." (PMID 38243188, 2024). "Consequently, it is hypothesized that the concurrent administration of FFAR4 agonist and glycolysis inhibitors could serve as a viable therapeutic approach for lung adenocarcinoma." (PMID 38243188, 2024). "Consequently, the involvement of FFAR4 in lung adenocarcinoma remains uncertain." (PMID 38243188, 2024). "Our experimental findings demonstrate that the activation of FFAR4 in lung adenocarcinoma cells leads to a noteworthy decline in the NAD+/NADH ratio and leads to dysfunction of OXPHOS, disrupting cellular energy balance and slowing down the proliferation of lung adenocarcinoma cells." (PMID 38243188, 2024).
lung disease (2 papers, 2020 to 2023). "Future directions for this work include determining the pathway effectors for this FFAR4-mediated regulation of pulmonary immunity and epithelial homeostasis in order to identify the potential of FFAR4 therapeutics in the treatment of lung disease." (PMID 37108233, 2023). "Ultimately, the presence of FFAR4 in the lung may regulate cell survival and repair following immune injury, suggestive of potential therapeutic directions for pulmonary disease." (PMID 37108233, 2023).
morbid obesity (2 papers, 2014 to 2023). An excess of body weight, normally defined as an individual with a body mass index greater than 35 or a body weight greater than one hundred percent of ideal body weight. "In humans, Ffar4 expression is increased in adipose from obese individuals, and in a European cohort, the FFAR4 R270H inactivating polymorphism is associated with morbid obesity." (PMID 37075982, 2023).
periodontitis (2 papers, 2024). An acute or chronic inflammatory process that affects the tissues that surround and support the teeth. "MR analysis corroborated the inferences drawn from scRNA-seq, identifying ten causal gene markers associated with periodontitis, including LIMA1, PEA15, TMEM158, CMTM6, PDP1, FFAR4, VAC14, and ENHO." (PMID 39830509, 2024).
Sepsis (2 papers, 2014 to 2022). Sepsis is defined as life-threatening organ dysfunction caused by a dysregulated host response to infection. "In the study, TUG-891 upregulated the FFAR4 mRNA and protein expression in cisplatin, sepsis, and IRI-induced injury kidneys, respectively." (PMID 36450712, 2022).
alcoholic hepatitis (1 paper, 2021). Acute hepatitis resulting from ingestion of alcohol. "More recently, omega-3 fatty acids, which are known agonists of FFAR1 and FFAR4, have shown efficacy in treating NAFLD, NASH, alcoholic hepatitis, and IFALD." (PMID 33897464, 2021).
asthma (1 paper, 2022). "We investigated whether free fatty acid receptor 4 (FFA4, also known as GPR120) is a molecular target for beneficial PUFA in asthma therapy." (PMID 35563671, 2022).
atrial fibrillation (1 paper, 2024). A disorder characterized by an electrocardiographic finding of a supraventricular arrhythmia characterized by the replacement of consistent P waves by rapid oscillations or fibrillatory waves that vary in size, shape and timing and are accompanied by an irregular ventricular response. "Thus, it is likely that expression of FFAR4 in the atrium may change in the pathological conditions such as in atrial fibrillation, suggesting the importance of FFAR4 density in the evaluation of EPA action on the pathological condition of the heart." (PMID 39062812, 2024).
chronic lung disease (1 paper, 2023). According to the definitions of the American and British Thoracic Societies, including pulmonary functional tests, X-rays, and CT scans for items such as fibrosis, bronchiectasis, bullae, emphysema, nodular or lymphomatous abnormalities. "This study clarifies the impact of FFAR4 on the inflammatory process through repair, with the long-term objective of ultimately identifying potential therapeutics, such as against DHA and FFAR4, and interventions for chronic lung diseases, for which few current therapeutics are available." (PMID 37108233, 2023).
dysplasia (1 paper, 2023). A usually neoplastic transformation of the cell, associated with altered architectural tissue patterns. "We identified that DHA mediates anti-inflammatory effects independent of FFAR4 expression, and that DE-exposed mice lacking FFAR4 had reduced immune cells in the airways, epithelial dysplasia, and impaired pulmonary barrier integrity." (PMID 37108233, 2023).
eating disorder (1 paper, 2023). A broad group of psychological disorders with abnormal eating behaviors leading to physiological effects from overeating or insufficient food intake. "Finally, numerous studies concluded that FFAR1 and FFAR4, could plays a critical role in various physiologic homeostasis mechanisms especially the regulation of appetite, eating disorder, or food preference." (PMID 36941594, 2023).
emphysema (1 paper, 2025). "H&E staining indicated the alleviating effect of Ffar4 on CS‐induced emphysema, with reduced lung destruction and lower MLI in Ffar4‐overexpressing mice and TUG891‐treated mice compared to the CS group." (PMID 40895192, 2025). "In summary, the results suggest that overexpression of Ffar4 or treatment with TUG891 can effectively mitigate the decline in lung function, emphysema, airway inflammation, and bronchial epithelial senescence induced by CS exposure in mice." (PMID 40895192, 2025).
epithelial dysplasia (1 paper, 2023). "We sought to identify if the FFAR4-dependent epithelial dysplasia had functional consequences for barrier integrity." (PMID 37108233, 2023). "Though not as pathological a phenotype as in the MyD88 KO, this reduced Md2 and Irf7 expression could contribute to MyD88-dependent dampened BAL infiltration and epithelial dysplasia in the Ffar4-null mice from our studies." (PMID 37108233, 2023).
Impaired glucose tolerance (1 paper, 2023). An abnormal resistance to glucose, i.e., a reduction in the ability to maintain glucose levels in the blood stream within normal limits following oral or intravenous administration of glucose. "Akkermansia muciniphila supplementation significantly improved the impaired glucose tolerance at ZT12 in mice with gut-specific Ffar4 deletion and was accompanied by recovery of serum hormone level and transcripts of key genes in glucose metabolism." (PMID 37787527, 2023).
ischemia reperfusion injury (1 paper, 2022). Adverse functional, metabolic, or structural changes in ischemic tissues resulting from the restoration of blood flow to the tissue (reperfusion), including swelling; hemorrhage; necrosis; and damage from free radicals. "In the study, the expression of FFAR4 was abnormally decreased in tubular epithelial cells (TECs) of cisplatin, cecal ligation/perforation and ischemia/reperfusion injury-induced AKI mice, respectively." (PMID 36450712, 2022).
laryngeal carcinoma (1 paper, 2021). Carcinoma that arises from the laryngeal epithelium. "FFAR4 can promote cell proliferation and migration and has been identified as a potential prognostic biomarker for laryngeal cancer." (PMID 34760708, 2021).
Peritoneal Fibrosis (1 paper, 2024). Disorder characterized by a wide range of structural changes in PERITONEUM, resulting from fibrogenic or inflammatory processes. "Treatment with omega-3 PUFAs restored FFAR4 expression, improving peritoneal fibrosis by inhibiting hyperglycolysis and the MMT via the activation of the FFAR4/CaMKKβ/AMPK pathway and the suppression of mTOR phosphorylation." (PMID 39457689, 2024).
serous ovarian carcinoma (1 paper, 2018). "High expression of both GPR65 and FFAR4 significantly correlated with lower survival in patients with serous ovarian carcinoma." (PMID 29712888, 2018).
cancer (26 papers, 2016 to 2025). A tumor composed of atypical neoplastic, often pleomorphic cells that invade other tissues. "Notably, the free fatty acid receptors FFAR1 (GPR40), FFAR2 (GPR43), FFAR3 (GPR41), and FFAR4 (GPR120) have the potential to bridge the genetic and environmental factors associated with cancer." (PMID 38243188, 2024). "We hypothesize that FFAR4 activation may be linked to the reprogramming of cancer metabolism, particularly the enhancement of glycolysis resulting in increased lactic acid production." (PMID 38243188, 2024). "Indeed, FFAR4 has been implicated as a regulator of the Hippo pathway in some cancers; however, there is little in the literature regarding this synergism in the lung." (PMID 37108233, 2023). "As shown in recently published studies, restoration of FFAR4 expression is crucial for anti-cancer effect because CRC cells with FFAR4 knockdown indicate an increase in proliferation." (PMID 39432182, 2024). "FFAR4 has been demonstrated to promote epithelial-mesenchymal transition, cell proliferation/migration, and drug resistance in various cancer types." (PMID 36746917, 2023). "This perspectiveaims to report recent research about GPR120/FFAR4 and its involvementin several diseases, including cancer, inflammatory conditions, andcentral nervous system disorders." (PMID 33843223, 2021). "In the Cancer Genome Atlas (TCGA) test dataset, eight genes were detected, and six of them were survival associated (DPP4, FFAR4, RASA3, RASGRF1, XCR1, and STX11)." (PMID 34760708, 2021). "Our results establish a novel role of FFAR4 and its ligands in the complicated interactions between tissue lipid profile and cancer biology." (PMID 30795784, 2019). "Consequently, in this manuscript, we discuss the anti-cancer properties of the FFAR4 agonist, GSK137647." (PMID 39432182, 2024). "Since cancer cells are known to “hijack” physiological functions of G protein-coupled receptors to serve their own purposes, we investigated whether cancer cells also exploit FFAR4 signaling." (PMID 30795784, 2019). "The aim of our study was to evaluate the anti-cancer effect of FFAR2 and FFAR4 stimulation by selective synthetic agonists in in vitro and in vivo models of CRC." (PMID 39432182, 2024). "Finally, considering the existence of FFAR4 in several human malignancies, we advise caution in the use of FFAR4 agonists or commercially available fish oil products for treatment of metabolic and inflammatory diseases in cancer patients due to systemic consequences." (PMID 30795784, 2019). "Similar to cancer cells, macrophages, and hepatocytes, we find that external fatty acids also upregulate HILPDA protein levels in adipocytes, which was mediated at least partly via FFAR4." (PMID 37422000, 2023). "Furthermore, some of the studies employed ω-3 PUFA esters, which cannot activate FFAR4 as they lack the carboxyl group, an indispensable structure for FFAR4 stimulation, yet observed anti-cancer effects nonetheless." (PMID 30795784, 2019). "FFAR2 agonist, 4-CMTB, and FFAR4 agonist, GSK137647 significantly decreased both non-cancer (CCD 841 CoN) and cancer (SW-480) cell growth at the concentrations 10–200 μM as compared to untreated cells." (PMID 39432182, 2024). "Furthermore, we previously found that FFAR4 is not required for n3-PUFA-induced cell growth inhibition and apoptosis in cancer cells." (PMID 37787527, 2023).